RIPK3 (receptor interacting serine/threonine kinase 3)
Diseases named in the same sentence as RIPK3 in open-access papers (continued):
Sharing a sentence is not in itself a finding about the gene and the disease.
colitis (continued). "In this study, we have analyzed the contribution of necroptosis to the enhanced susceptibility of ADAM17ex/ex mice to intestinal damage in DSS-induced colitis, and in particular whether this susceptibility can be ameliorated by deletion of the necroptotic core protein RIPK3." (PMID 29560122, 2018). "In a previous study, we found increased necroptosis in the colon of an experimental colitis mouse model, but this was alleviated by RIPK3 inhibition." (PMID 40821844, 2025). "RIPK3 and MLKL deficiency was reported to inhibit DSS-induced colitis, and MLKL or the RIPK3/necroptosis axis is a driving force for intestinal inflammation." (PMID 40877233, 2025). "Necroptosis increases in mice with colitis, and the suppression of necroptosis via RIPK3 inhibition alleviates the disease." (PMID 40821844, 2025). "The severity of inflammation in experimental colitis was found to be exacerbated by a defect in either RIPK3 or MLKL, leading to necroptosis." (PMID 40877233, 2025). "In experimental colitis, RIPK3 inhibitors decrease inflammatory cytokines and improve weight loss, survival, and colon length." (PMID 39118979, 2024). "We have shown that Gab1 ablation in IECs contributed to the aggravated colitis due to excessive RIPK3-dependent necroptosis." (PMID 36795486, 2023). "Taken together, these data indicate that hyperactivation of RIPK3 and necroptosis in IECs is primarily responsible for the exacerbated colitis in Gab1IEC-KO mice." (PMID 36795486, 2023). "Wu-Mei-Wan alleviates TNBS-induced colitis in mice by inhibiting necroptosis through increasing RIPK3 O-GlcNAcylation." (PMID 37238692, 2023). "Inducible and conditional deletion of the CTα encoding gene Pcyt1a rendered mice susceptible to spontaneous colitis, increased number of TUNEL-positive cells in the colon, and increased RIPK3 mRNA and protein levels." (PMID 37409125, 2023). "In the meantime, the survival curve demonstrated that RIPK3-/- and MLKL-/- mice were susceptible to DSS-induced colitis." (PMID 37691056, 2023). "Collectively, these results indicate that DC-specific RIPK1 deletion confers the protection against DSS-induced colitis in a FADD-dependent but RIPK3-MLKL-independent manner." (PMID 34462571, 2022). "RIPK3 inhibitor ameliorates the severity of experimental colitis and reduces inflammation through the inhibition of the inflammatory response and necroptosis and supports RIPK3-targeting substances for the treatment of UC." (PMID 36431783, 2022). "Increasing evidences show that RIPK3 contributes to the pathologies of inflammatory diseases including multiple sclerosis, infection and colitis." (PMID 35217652, 2022). "Previous investigations have demonstrated that RIPK3 accumulation correlates with severe IECs necroptosis and colitis." (PMID 35110556, 2022). "VDR inhibits necroptotic apoptosis, alleviates inflammation, and suppresses the induction of colitis by preventing receptor interacting serine/threonine kinase 3 (RIPK3) from binding to RIPK1." (PMID 34588980, 2021). "Taken together, increasing RIPK3 O-GlcNAcylation can reduce RIPK3 activation, thereby inhibiting necroptosis, finally alleviating colitis." (PMID 34399822, 2021). "From above results, we can conclude that WMW alleviates TNBS-induced colitis by inhibiting necroptosis through increasing RIPK3 O-GlcNAcylation." (PMID 34399822, 2021). "Our work demonstrated that WMW can alleviate TNBS-induced colitis in mice by inhibiting necroptosis through increasing RIPK3 O-GlcNAcylation." (PMID 34399822, 2021). "After confirming the protective effects of WMW on colitis are mediated by its promotion of RIPK3 O-GlcNAcylation, we preliminarily explored the underlying mechanisms of WMW on RIPK3 O-GlcNAcylation." (PMID 34399822, 2021). "Hesperetin, a flavonoid from citrus fruits inactivates RIPK3/MLKL signaling improving the DSS-induced colitis in mice." (PMID 33050394, 2020).
colitis (continued). "Despite the loss of RIPK3, ADAM17ex/ex/RIPK3−/− mice showed the same increased susceptibility as ADAM17ex/ex mice in both acute and chronic models of DSS-induced colitis." (PMID 29560122, 2018). "In addition, in DSS-induced colitis, the DJ-1 deficiency-induced activation of p-RIPK1, p-RIPK3 and p-MLKL was dramatically blunted in the DKO mice." (PMID 40877233, 2025). "Moreover, hesperetin has been demonstrated to greatly lessen the manifestations of DSS-induced colitis, suppress RIPK3 and MLKL expression, and deactivate their necroptosis signaling pathways." (PMID 39118979, 2024). "A number of genetic studies reveal that mice with genetic ablation of Caspase-8, Fas associated via death domain (Fadd), or SET domain bifurcated histone lysine methyltransferase 1 (Setdb1) in IECs develop spontaneous ileitis and colitis owing to sensitizing cells to RIPK3-mediated necroptosis." (PMID 36795486, 2023). "Hesperidin could significantly reduce DSS-induced colitis injury by increasing the expression of ZO-1 and reducing the expressions of inflammatory factors, RIPK3 and MLKL." (PMID 36431783, 2022). "In direct contrast, Newton and colleagues have likewise investigated DSS-induced colitis in RIPK3-deficient mice, and found no impact of loss of RIPK3 at all, i.e., RIPK3−/− and WT mice showed identical responses." (PMID 29560122, 2018). "WB analysis showed that the level of p-RIPK3 in colitis group was also increased." (PMID 29156831, 2017). "We therefore postulated that RIPK3 might protect from colitis-driven CRC by dampening immune cell infiltration, activation and inflammatory responses." (PMID 27344176, 2016). "As such, Ripk3−∕− BMDCs were highly defective in expression of many inflammatory cytokines including IL-1β and IL-23, the two key repair-associated cytokines in the DSS-induced colitis model." (PMID 27446921, 2016). "Inhibiting RIPK3 activity has been extensively explored by many researchers as a direction for suppressing necroptosis and proved effective; furthermore, boosting RIPK3 O-GlcNAcylation can diminish RIPK3 activation, thereby inhibiting necroptosis and ultimately relieving colitis." (PMID 37836654, 2023). "Collectively, our study defines a protective role for Gab1 in colitis and colitis-driven colorectal cancer by negatively regulating RIPK3-dependent necroptosis, which may serve as an important target to address necroptosis and intestinal inflammation–related disease." (PMID 36795486, 2023). "Moreover, pharmacological inhibition of RIPK3 substantially alleviated experimental colitis with reduced inflammation in Gab1IEC -KO mice, suggesting that hyperactivation of RIPK3 and necroptosis largely contributes to exacerbated colitis in epithelial Gab1-deficient mice." (PMID 36795486, 2023). "Therefore, additional work needs to do that excludes the possibility that HG-9-91-01 may bypass SIKs to inhibit RIPK3 kinase activity to functions in murine experimental colitis, melanin production, gluconeogenesis andβcell proliferation." (PMID 35217652, 2022). "Interestingly, Ripk3 knockout mice in a dextran sulfate sodium (DSS)-induced colitis model had enhanced sensitivity, suggesting that RIPK3 may also have tissue regenerative functions." (PMID 30842945, 2019). "Since our results implicate that necroptotic signaling is already compromised in ADAM17ex/ex mice in the first place, it is not possible to determine whether the pro-necroptotic functions of RIPK3 are important or dispensable for the course of colitis in these mice." (PMID 29560122, 2018). "Given the pronounced response that we had seen in ADAM17ex/ex and ADAM17ex/ex/RIPK3−/− mice in the acute colitis model, we speculated that the employed treatment regimen of 1.5% DSS might have overpowered any protection that lack of RIPK3 might have conferred to the ADAM17ex/ex/RIPK3−/− mice." (PMID 29560122, 2018). "The activation of the RIPK3/MLKL pathway has been well-confirmed in human IBD and murine model of colitis." (PMID 40745657, 2025).
colitis (continued). "Similarly, a RIPK3 inhibitor has been shown to mitigate the intensity of experimental colitis and decrease inflammation through the suppression of the inflammatory response and necroptosis, indicating that RIPK3 may be involved in the pathogenesis of necroptosis-induced UC." (PMID 39118979, 2024). "The colitis drug GSK-872 reduces the severity of the condition, minimizes inflammation, and supports UC medications that target RIPK3." (PMID 39118979, 2024). "In the same way, celastrol administration has been found to relieve the severity of colitis by decreasing IL-1β, IL-6, myeloperoxidase (MPO), RIPK3, and MLKL levels while increasing active caspase-8 levels and E-cadherin." (PMID 39118979, 2024). "Conversely, supplementation of GSK872 remarkably suppressed the phosphorylation of RIPK3 and MLKL in CKO T cells during colitis." (PMID 36721037, 2023). "Another recent study supports the involvement of necroptosis in DSS-induced colitis, since the authors showed that GAB1 is involved in RIPK3 dephosphorylation and inhibition of IEC necroptosis using a DSS colitis model." (PMID 37409125, 2023). "The traditional herbal formula Wu-Mei-Wan inhibits necroptosis in mice by increasing RIPK3 O-GlcNAcylation, thus alleviating TNBS-induced colitis." (PMID 37238692, 2023). "Consistently, mice with conditional deletion of caspase 8 or FADD in intestinal epithelium developed spontaneously colitis that was dependent on MLKL and RIPK3-mediated epithelial cell necroptosis." (PMID 35217652, 2022). "Our results demonstrated that WMW can enhance OGT activity and suppress OGA activity, thereby increasing RIPK3 O-GlcNAcylation, and then inhibiting necroptosis, eventually alleviating TNBS-induced colitis." (PMID 34399822, 2021). "In colitis model, we determined an inhibition of RIPK3 and MLKL during necroptosis in the inflamed epithelium, whereas a down-regulation of RIPK3 and MLKL was observed in the M10-treated epithelium." (PMID 33041798, 2020). "In the TNBS-induced colitis in mice, TUNEL-positive and caspase-3-negative cells were observed in the intestinal mucosa, and p-RIPK3 was found to be elevated." (PMID 29156831, 2017). "In a model of spontaneous colitis using FADD-knockout mice, RIPK3 knockout prevented the development of spontaneous disease in the small intestine and colon." (PMID 29156831, 2017). "In the model of TNBS-induced colitis, we observed cell death characterized by necrosis (TUNEL-positive and caspase-3-negative) and elevated p-RIPK3 in the intestinal mucosa." (PMID 29156831, 2017). "It has been reported that RIPK3 within dendritic cells (DCs) promotes injury-induced inflammation and tissue repair in the dextran sulfate sodium (DSS) model of colitis, partly through an IL-23, IL-1β, and IL-22 axis." (PMID 27344176, 2016). "Interestingly, RIPK3-deficient mice had increased Wnt-β-catenin signaling shown by induction of genes important for IEC survival, proliferation and invasiveness (cMyc, Cox2 and Wisp1), and cell cycle progression (Cyclin B1, Cyclin D1, Cyclin E and p21) during colitis-associated CRC." (PMID 27344176, 2016). "Our results support that IPA, a bacterial metabolite, may block the epithelial necroptosis by inhibiting the RIPK1/RIPK3/MLKL pathway, which may give a rational explanation for the lower concentration of its in both colonic tissue and serum of colitis." (PMID 40745657, 2025). "Furthermore, the traditional Chinese medicine formulation Wumei Pill (WMW) alleviated colitis in mice by enhancing OGT activity, thereby increasing RIPK3 O-GlcNAcylation, disrupting RIPK3-MLKL interactions, and suppressing necroptosis." (PMID 41280891, 2025). "As a result, WMW could prevent necroptosis through promoting RIPK3 O-GlcNAcylation and suppressing the binding of RIPK3 and MLKL, ultimately alleviating TNBS-induced colitis in mice." (PMID 39840043, 2024). "We found that ABIN1, RIPK1, RIPK3, and MLKL were upregulated in UC samples and DSS-induced colitis." (PMID 36034412, 2022).
colitis (continued). "We found that ABIN1, RIPK1, RIPK3, and MLKL were upregulated in UC sample and DSS-induced colitis." (PMID 36034412, 2022). "The increased colonic inflammation and the resistance to colitis were restored by dual inactivation of RIPK3 and FADD, but not by inhibition of RIPK3, MLKL, or ZBP1 alone." (PMID 34462571, 2022). "Indeed, CRIF1 overexpression reduced the numbers of cells expressing TNF-α, TNFR1, RIPK1, RIPK3, and phosphorylated MLKL in our experimental mice, suggesting that CRIF1 overexpression can downregulate intestinal inflammatory cell death in colitis." (PMID 40821844, 2025). "Additionally, RIPK3 inhibitors have been shown to reduce the necrosis of CD4 + T cells, differentiation of Th17 cells, and expression of pro-inflammatory cytokines, all of which are important colitis-inducing factors." (PMID 38684668, 2024). "Interestingly, RIPK3 activity can be restricted by ubiquitination of the beyond-the-RHIM (BTR) domain, and its TSC1/mTOR - TRIM11-mediated ubiquitination and degradation in IECs alleviates necroptosis and hence colitis." (PMID 37409125, 2023). "Thus, IEC lacking caspase-8 or FADD due to epithelial cell-specific deletion underwent RIPK3-dependent necroptosis instead of apoptosis in response to TLR or TNF stimulation, leading to a complete absence of Paneth cell, serious tissue damage, enteritis and severe erosive colitis in vivo." (PMID 39840043, 2024). "Our data demonstrate that in the absence of RIPK3, colonic inflammation was increased as was the tumor incidence and size following AOM-DSS treatment, indicating that RIPK3 has a fundamental role in inhibiting intestinal inflammation and colitis-associated CRC development." (PMID 27344176, 2016). "In our GEO data analysis of UC patients, “Pyroptosis”, “Regulated necrosis”, and “Apoptosis” were positively correlated with UC patients, which supports our result showing increased expression of RIPK1 and RIPK3, but not ALOX12 and GPX4, in the acute colitis model." (PMID 38491049, 2024). "The results showed that RI-962 reduced the levels of pRIPK1, pRIPK3, and pMLKL proteins in the colon during DSS challenge, but did not impact the expression of RIPK1, RIPK3, and MLKL proteins, suggesting that RI-962 suppressed the RIPK1 signaling in the mouse model of DSS-induced colitis." (PMID 36371441, 2022). "Although pBcl-2 was not detectable for unknown reasons in ADAM17ex/ex/RIPK3−/− mice, cleaved caspase-3 displayed an increased signal in samples from DSS-treated ADAM17ex/ex mice, showing that unlike necroptosis, apoptosis is induced in ADAM17ex/ex mice in the course of acute colitis." (PMID 29560122, 2018).
melanoma (39 papers, 2013 to 2025). A malignant, usually aggressive tumor composed of atypical, neoplastic melanocytes. "Although RIPK1 and MLKL levels are homogeneous in most melanoma cell lines, the expression of RIPK3 is extremely low, which has been associated with the absence of necroptosis." (PMID 40710498, 2025). "In larger melanoma datasets, this observation should be verified to confirm the utility of RIPK3 as an early diagnostic biomarker." (PMID 38397165, 2024). "Our data now explain the loss of expression of RIPK3 in malignant melanoma, by highlighting that RIPK3 is an epigenetically silenced tumor suppressor." (PMID 38397165, 2024). "In melanoma, selective inhibition of the RIPK3/MLKL axis by loss of RIPK3 is essential to prevent necroptosis." (PMID 35610275, 2022). "Our investigations demonstrate for the first time that loss of RIPK3 during melanoma development is critical for necroptosis protection." (PMID 26355347, 2015). "Indeed, we found that loss of RIPK3 in melanoma cells phenocopied the ICI immunotherapy resistance of MLKL-deficient tumors." (PMID 40345706, 2025). "Similarly, low expression of RIPK3 in tumor biopsies was linked to poor overall survival in patients with malignant melanoma." (PMID 40345706, 2025). "For the first time, it has now become clear that RIPK3 acts as an epigenetically regulated tumor suppressor in melanoma; its re- or overexpression likely causes an induction of necroptosis, which results in an inhibition of tumor cell proliferation in melanoma and HEK." (PMID 38397165, 2024). "Necroptosis plays different roles in different cancers, with necroptosis-associated protein RIPK3 being expressed at low levels in leukemia, colorectal cancer, breast cancer and melanoma relative to adjacent normal tissues, and at increased levels in lung cancer and pancreatic cancer." (PMID 36159818, 2022). "In melanoma cells with active melanogenesis, the use of melanin synthesis inhibitors to induce depigmentation could also restore the susceptibility of melanoma cells to RIPK1/RIPK3/MLKL-mediated necroptosis." (PMID 35359389, 2022). "Evidence indicates that RIPK3 is expressed at lower levels in melanoma cell lines, but higher in normal melanocytes and benign nevi." (PMID 40497999, 2025). "C57BL/6 J mice bearing RIPK3−/− melanomas showed diminished tumor control and poor survival when undergoing combined therapy with anti-PD-1 and anti-CTLA-4." (PMID 40345706, 2025). "RIPK3 expression was strongly reduced in tumor samples of skin cancer (malignant melanoma, The Cancer Genome Atlas Program (TCGA)) in comparison to normal control skin samples." (PMID 38397165, 2024). "We observed low RIPK3 methylation of naevi and increasing methylation for primary melanoma, metastases, and melanoma cell lines." (PMID 38397165, 2024). "In this study, the potential tumor suppressor gene Receptor Interacting Serine/Threonine Protein Kinase 3 (RIPK3) was examined for an epigenetic regulation and its gene inactivation in melanomas." (PMID 38397165, 2024). "Methylation heatmaps generated with data from Illumina Methylation Assay-450k-Array showed an increased methylation rate of the CpG probes in the CpG island of RIPK3 in metastatic melanomas as well as in melanoma cell lines in comparison to normal tissues." (PMID 38397165, 2024). "Our additional experiments focused on supporting the tumor suppressor role of RIPK3 in melanoma and kidney." (PMID 38397165, 2024). "Our data highlight the function of RIPK3 as an epigenetically regulated tumor suppressor in melanoma, allowing it to be classified as a biomarker." (PMID 38397165, 2024). "We analyzed the CpG island of RIPK3 that is located downstream of its promoter to assess the status of RIPK3 hypermethylation in malignant melanomas." (PMID 38397165, 2024). "In HEK and in all melanoma cell lines examined, deterioration in cell morphology was observed with increased RIPK3 levels." (PMID 38397165, 2024).